MMP9 (matrix metallopeptidase 9)
Diseases named in the same sentence as MMP9 in open-access papers (continued):
Sharing a sentence is not in itself a finding about the gene and the disease.
cancer (continued). "Both wild-type and mutant FAPs caused comparable increases in cancer-related signaling pathways and the expression of matrix metalloproteinase 9 (MMP9), suggesting that FAP might exert intrinsic effects on cellular signaling independently of its enzymatic activity." (PMID 39765634, 2024). "Therefore, regulating the expression and activity of MMPs, especially MMP-2 and MMP-9, could be a promising strategy to reduce the risk of cancers." (PMID 38672151, 2024). "In contrast, the positive expression of MMP-9 was relatively strong in nPDA-cis plates and porous nPDA-cis balls, indicating that these two configurations of nPDA-cis may have the risk of promoting cancer cell invasion and metastasis." (PMID 39027362, 2024). "MMP9-related cutting of the E-cadherin extracellular domain results in the reduction of its surface levels and the loss of stable cell–cell junctions, apico-basal membrane polarity, and epithelial architecture, which allows cancer cells to escape from their primary sites." (PMID 35406619, 2022). "The gelatinase protein family including MMP2 (gelatinase A) and MMP9 (gelatinase B) are able to degrade type IV collagen in basement membranes and are the most extensively studied metalloproteinases that are associated with disease progression and poorer survival in patients with various cancers." (PMID 36591235, 2022). "Furthermore, the potential migration and invasion inhibitions by the ethanolic extract of the Egyptian B. nigra was also evidenced by the downregulation of MMP2, MMP9, and Snail genes, and the upregulation of the E-cadherin gene (hallmark of cancer metastasis)." (PMID 35956938, 2022). "Indeed, in cancer patients, a high MMP-9 level is linked to a poor prognosis." (PMID 35463960, 2022). "Further, genetic variation influencing MMP9 expression could contribute to cancer susceptibility." (PMID 33573134, 2021). "In addition, activated MMP-2 and MMP-9 is associated VEGF bioavailability in cancer." (PMID 32353975, 2020). "Furthermore, MMP-2 and MMP-9 were closely associated with the poor outcome of cancer patients." (PMID 30931081, 2019). "MMP-9 not only plays a key role in the development of cancers, but also their characteristics of being secreted into the blood stream have inspired many researchers to evaluate the associations between circulating level of MMP-9 and clinicopathological characteristics of cancers." (PMID 31038586, 2019). "Here, we report a molecular axis, comprising the molecular adaptor hydrogen peroxide-inducible clone-5 (HIC-5), NADPH oxidase 4 (NOX4), and mitochondria-associated reactive oxygen species (mtROS), that regulates MMP9 expression and may be a target to suppress cancer metastasis." (PMID 30281903, 2018). "Thus, induction of Casp12/NF-κB signaling might be associated with MMP-9-induced aggressive metastasis in carcinoma cell." (PMID 28380444, 2017). "There is evidence that VEGF promotes the secretion of some enzymes that facilitate the metastasis of cancers, and that overexpression of VEGF can induce MMP-2 and MMP-9, which may be a major mechanism underlying the invasion and metastasis of highly invasive cancers." (PMID 27153056, 2016). "Thus, a cross-talk between N-cadherin and MMP-9 might be implicated in enhanced carcinoma cell invasion." (PMID 27737648, 2016). "Indeed, in many cancers RECK down-regulation is associated with high levels of MMP-9." (PMID 25432084, 2014). "The therapeutic efficacy was initially analyzed on HeLa cells as a cancer model due to their high transfection efficiency, reproducibility, and overexpression of MMP-9, using doxorubicin (Dox) as the drug." (PMID 42205116, 2026). "Inflammation‐induced NETosis reactivates dormant cancer cells by releasing proteases (neutrophil elastase and MMP9) that remodel laminin and activate integrin signalling, leading to metastasis." (PMID 41503514, 2026). "•MMP-2 and MMP-9 Regulation: Knockdown of MEG3 increased MMP-2 and MMP-9 expression, promoting cancer cell invasion." (PMID 41480643, 2026).
cancer (continued). "Elevated MMP-2 and MMP-9 have been consistently correlated with poor outcomes and metastatic progression in ovarian and other cancers, and our observations reinforce this established paradigm." (PMID 41480643, 2026). "Our successful application of the system to differentially profile PD-L1 and MMP9 expression on exosomes from three distinct cancer cell lines and a non-cancerous control highlights its potential as a powerful tool for cancer diagnostics." (PMID 41302727, 2025). "The mechanism was mediated through ECM1 and MMP9 activation, genes known for cancer invasiveness and aggressiveness." (PMID 40870446, 2025). "An increase of miR-21 expression can upregulate MMP9 levels through indirect mechanisms, primarily by suppressing negative regulators of signalling pathways that control MMP9 transcription, inducing cancer progression." (PMID 41240165, 2025). "The suppression of matrix metalloproteinases MMP-2 and MMP-9, enzymes essential for extracellular matrix degradation and cancer cell invasion, has been observed following treatment with aronia polyphenols." (PMID 41515306, 2025). "Mechanistically, cancer cells exposed to chemotherapy, release IL-1β that triggers NET formation, along with integrin αvβ1 and MMP9 that, associated with NETs, unleash and activate latent TGFβ." (PMID 41360771, 2025). "In bladder cancer, the PI3K/Akt/STAT3 signaling pathway, which induces MMP-2 and MMP-9 expression, is crucial for enhancing the migration and invasion of cancer cells promoted by B7-H3." (PMID 40214484, 2025). "Our results demonstrate that inhibition of MMP-9 by the endogenous MMP inhibitor N-TIMP2 and its engineered variant REY effectively suppresses cancer cell proliferation, invasion, and spheroid spread in U251 GB cells." (PMID 41154699, 2025). "In gastric adenocarcinoma cells, RA reduced the activity of MMP-9, which is crucial for cancer spread because it breaks down collagen and other extracellular matrix proteins." (PMID 40427522, 2025). "Among these, multiple flavonols in wine have been reported as regulators of MMP-2 and MMP-9, enzymes involved in cancer progression." (PMID 40563423, 2025). "Due to the key role of Mmp9 in cancer pathways and the ECM-receptor interaction pathway, the Mmp9 expression and methylation status in offspring lungs were examined." (PMID 41150507, 2025). "In some cancer models (e.g., leukemia and glioma), Rh1 can induce differentiation of cancer cells, reduce expression of metastasis-related factors like MMP-9, and augment immune-mediated cytotoxicity, making it an intriguing adjunct in oncology." (PMID 40709093, 2025). "An in vitro study conducted on SCC HNC cell lines showed that extracts from Ocinum sanctum leaves can decrease the activity of MMP-2 and MMP-9 metalloproteinases, thus significantly reducing cancer cell invasion (p < 0.05)." (PMID 40282445, 2025). "Overexpression of MMP-9 was observed in various cancers, including breast, gastric, non-small-cell lung, prostate, and OSCC." (PMID 40017656, 2025). "Due to the crucial role of MMP-2 and MMP-9 in cancer progression, targeting their regulation has emerged as a promising therapeutic approach." (PMID 40563423, 2025). "The control group showed normal MMP-9 levels, while the cancer group showed a significant increase in MMP-9 levels (61.55 ± 3.40)." (PMID 40008130, 2025). "Our in silico analysis of the human proteome further demonstrated that MMP9 exhibits a restricted expression pattern in healthy tissues, underscoring its potential for precise cancer targeting." (PMID 41041068, 2025). "Among them, MMP‐9 (also termed gelatinase B) plays a pivotal role in cancer growth and progression; therefore, it is considered a potential biomarker for the diagnosis and evolution of different types of cancers." (PMID 40304052, 2025).
cancer (continued). "Since the MMP-9 enzyme is a central target in the treatment of inflammatory diseases, various types of cancers, and neurological disorders, finding appropriate inhibitors can aid in combating these diseases." (PMID 40718443, 2025). "The role of circDENND4C, miR-200b, and MMP-9 in cancer progression has been extensively studied in previous studies." (PMID 40034591, 2025). "MDSCs protect cancer cells by suppressing immunosurveillance, promoting angiogenesis via the secretion of matrix metallopeptidase 9 (MMP9) and the vascular endothelial growth factor (VEGF), and inducing metastasis." (PMID 39308084, 2025). "Extensive research has shown that MMP-9 is markedly upregulated in various human malignancies and plays a crucial role in the proliferation and metastasis of cancer cells." (PMID 40365275, 2025). "Clinical trial results have shown that MMP‐9 serum concentrations are significantly elevated in malignant tumor patients." (PMID 40808216, 2025). "In this review, we summarize and discuss how bioactive molecules in wine regulate MMP-2 and MMP-9 through bioactive compounds derived from wine and explore their implications for cancer treatment." (PMID 40563423, 2025). "MMP-9 has been previously shown to be present in 160- to 200-nm vesicles in N2a neuronal cells and in dense-core vesicles in cancer cells." (PMID 40991708, 2025). "Within the MMP family, MMP‐2 and MMP‐9 are particularly significant, as their release by cancer cells facilitates matrix degradation, thereby promoting infiltration, invasion, and distant metastasis." (PMID 39834553, 2025). "The increased expression of MMP-9 is a poor prognosis factor for cHL by promoting cancer cell migration." (PMID 41296384, 2025). "The group in which cancer cells were treated with 4000 EVs per cell showed a decrease in MMP9 and TIMP1 gene expressions, whereas the group with 12,000 EVs per cell showed no significant change." (PMID 40208413, 2025). "They proposed a nuanced mechanism through which NETs rouse these quiescent cells: NE and MMP-9 derived from NETs cleave and remodel laminin, activating the integrin α3β1 signaling pathway and fostering cancer cell proliferation." (PMID 40365275, 2025). "To investigate the impact of MMP-9 inhibition on the invasion of U251 GB cells, we performed Matrigel transwell assays that measure the ability of cancer cells to migrate through an ECM barrier." (PMID 41154699, 2025). "We examined the roles of HIF-1α, MMP-9, and β-catenin as cancer-promoting factors, and we observed that the levobupivacaine treatment affected the expressions of HIF-1α and MMP-9 in an ACE2-dependent manner, whereas β-catenin was regulated independently." (PMID 41303321, 2025). "Studies have found that AMPK modulates the transcriptional activity of MMP‐9 through selective autophagy and activation of Nrf2, thereby aiding cancer cells in surviving metabolic stress." (PMID 40583724, 2025). "FAK/Src pathway induces Akt activation in cancer cells, leading to high secretion of MMP-2 and MMP-9, which eventually causes proliferation, migration, invasion, and metastasis." (PMID 40040878, 2025). "MMP-9, an enzyme that breaks down extracellular matrix components to promote cancer cell invasion and metastasis, is one of its well-established targets." (PMID 40943427, 2025). "The inhibition of NMBR using BIM-23127 and the inhibition of MMP9 with MMP9-i have demonstrated similar functions in cancer and oseltamivir and peramivir on SARS-CoV-2 infection progression." (PMID 40227834, 2025). "Both SLPI and MMP-9 are involved in inflammation and the link between them was reported in the context of as cancer and lung diseases." (PMID 40496854, 2025). "Some clinical investigation reveals a novel mechanism of ADAM15 in promoting cancer cell invasion through directly targeting MMP9." (PMID 40725774, 2025).
cancer (continued). "Actually, in breast cancer, non‐small cell lung cancer, ovarian cancer, pancreatic cancer, and osteosarcoma, the upregulation of MMP‐9 displays a crucial role in cancer progression and metastatization." (PMID 40304052, 2025). "Given the important role of MMP-9 in cancer pathologies, the development of its inhibitors and targeting of MMP-9 is a current priority." (PMID 40718443, 2025). "Girdin, a cytoskeletal scaffold protein, regulates cancer cell motility, facilitating tissue invasion while MMP-9 remodels the ECM and breaks down barriers to enable metastasis." (PMID 39851541, 2025). "A previous study on other types of cancer has shown that melittin suppressed tumor necrosis factor (TNF)-induced MMP-9 activity by inhibiting the phosphorylation of p38 and ERK1/2 in human aortic smooth muscle cells." (PMID 40141020, 2025). "The control of vimentin, E-cadherin, vascular endothelial growth factor (VEGF), and matrix metalloproteinase-9 (MMP-9) expression forms the basis of the mechanism of action against cancer cells." (PMID 40427522, 2025). "Our results were consistent with previous studies on the role of circDENND4C, miR-200b, and MMP-9 in cancer cells." (PMID 40034591, 2025). "Pro-tumoral effects include acting as an intracellular iron carrier and safeguarding MMP9 from proteolytic degradation, which has been observed in various cancers such as those of the breast, brain, uterine cervix, esophagus, and stomach." (PMID 40277747, 2025). "Our results revealed the upregulation of IL6 in both the serum and cancer tissues of HCC patients, which was positively correlated with the protein level of MMP9 and linked to a worse prognosis." (PMID 39744421, 2025). "This review provides a focused synthesis of current knowledge regarding the regulatory effects of wine-derived bioactive compounds on MMP-2 and MMP-9 in the context of cancer progression." (PMID 40563423, 2025). "The functions of PD-L1 (immune escape) and MMP9 (physical invasion) represent two distinct yet complementary mechanisms of cancer progression." (PMID 41302727, 2025). "Isoginkgetin also inhibits cancer cell invasion by downregulating matrix metalloproteinase-9 (MMP-9) via the PI3K/Akt/NF-κB pathway." (PMID 39885614, 2025). "And neutrophil‐derived NETs and their associated molecules MMP9 and HMGB1 can also induce cancer cell proliferation." (PMID 40979214, 2025). "MMP9, while known to enhance cancer progression, can paradoxically inhibit growth and metastasis by cleaving signaling molecules, resulting in fragments that act as antagonists and block receptor activation." (PMID 40141751, 2025). "MMP-2 and MMP-9 are particularly significant in cancer metastasis as they primarily degrade gelatin and collagen IV and V, enhancing the invasiveness of cancer cells." (PMID 41356146, 2025). "To furthermore characterize the response of direct binding to VDAC1/PHB/MMP9 in cancer cells, we examined the effects of CRC cells on cell death and cell cycle." (PMID 41179704, 2025). "Gel electrophoresis measurements showed the reduction in MMP9 activity and indicated the potential of 1 in limiting the cancer cells’ invasion." (PMID 40149886, 2025). "Further analysis was conducted to evaluate the expression of matrix metalloproteinases (MMP-2 and MMP-9), enzymes critical for cancer cell invasion and metastasis." (PMID 39781358, 2025). "MMP9 elicit epithelial-to-mesenchymal transition in tumour cells, leading to more aggressive phenotype of cancer." (PMID 39941741, 2025). "Gold nanoparticles inhibited MMP-9 activity in prostate cancer cells, promoting anti-cancer cytokine secretion and exerting cytotoxic effects." (PMID 40284474, 2025). "This reduction leads to a decreased expression of downstream MMP2 and MMP9 proteases, which helps prevent cancer cell migration and metastasis." (PMID 40422575, 2025).
cancer (continued). "Previous studies have shown that halofuginone inhibits MMP-2 and MMP-9 in cancer and liver tissues, while SIS3 reduces TGFβ1-induced MMP activity in HCC1806 cells." (PMID 40535569, 2025). "Analysis of MMP-2 and MMP-9 levels in tissues from radical prostatectomy demonstrated that these metalloproteinases were significant warning signs of cancer recurrence." (PMID 40563423, 2025). "It should be noted that the same proteins (CD9, CD24, CD63, CD81, MMP9) were common to exosomes of cancer cells and primary cells." (PMID 40310419, 2025). "Our observation of ID1 regulating MMP9 secretion is of interest in cancer progression as it degrades the extracellular matrix and basement membrane components to promote cancer metastasis." (PMID 40116596, 2025). "In various pathological conditions, including inflammation and cancer, NF-κB can regulate cell migration and invasion by modulating MMP9 expression." (PMID 40699768, 2025). "p17 modulates MMP9 activity, underscoring its role in curbing the invasive behavior of cancer cells." (PMID 40575485, 2025). "Future studies should aim to define cancer-specific MMP9 glycoproteoforms with higher precision to enhance the specificity of non-invasive detection strategies." (PMID 41041068, 2025). "CD147 has been implicated in cancer cell migration and invasion through the induction of matrix metalloproteinases (MMPs), including MMP-2 and MMP-9." (PMID 41123660, 2025). "TMEM16F KO tumors also showed a reduction in MMP9, which exacerbates cancer progression by degrading extracellular matrix proteins." (PMID 40391322, 2025). "MMP-9 promotes cancer progression through basement-membrane degradation, induction of epithelial–mesenchymal transition, and growth-factor-driven angiogenesis, collectively enabling invasion, dissemination, and metastatic expansion." (PMID 41304763, 2025). "NET-derived proteases, such as NE and MMP-9, remodel laminin and activate integrin α3β1 signaling, promoting cancer cell proliferation." (PMID 40365275, 2025). "Among these, MMP-2 and MMP-9 are key proteins that promote cancer cell invasion by degrading type IV collagen, a major component of the basement membrane." (PMID 41471692, 2025). "The thymus of mice with cancer cachexia exhibited degradation of the thymic medulla and decreased expression of LtβR, Mmp9 and Ccl19 in thymus medullary fibroblasts (mFbs)." (PMID 40665793, 2025). "MMP-9 is a proteolytic enzyme essential for the disintegration of the extracellular matrix, which promotes the spread of cancer." (PMID 40427522, 2025). "This genesets includes MMP9, which is reported to promote cancer cell invasion, angiogenesis and disease progression in solid tumors." (PMID 41445746, 2025). "Preventing Cancer Spread: Curcumin lowers the activity of enzymes like MMP-2 and MMP-9, which help cancer cells invade surrounding tissues." (PMID 40649942, 2025). "HSP70 plays a role in cancer stemness by increasing the expression of cancer stemness-associated proteins (such as vimentin, N-cadherin, MMP-2, MMP-9, Snail, Slug, Twist, and others)." (PMID 41369386, 2025). "It suppressed the activity and expression of matrix metalloproteinases (MMPs), such as MMP-2 and MMP-9, which are critical for cancer cell invasion." (PMID 40136435, 2025). "Conversely, skimmianine-mediated TNF-α suppression reduced cancer progression, yet TNF-α-associated hub proteins (TNF-α, IL2, MMP9) remained positively correlated with immune infiltration, highlighting the dual role of TNF-α in the TME." (PMID 40430573, 2025). "MMP9 isa member of the multifunctional family of zinc-dependentendopeptidases and is activated during inflammation and incertain cancers." (PMID 41541554, 2025). "MMP9 emerged as the most cancer-specific protein, exhibiting minimal expression in normal tissues, particularly in adipose tissues and immune cells of the bone marrow, pancreas, spleen, and colon." (PMID 41041068, 2025).